UCP1 (uncoupling protein 1)
Description:
Mitochondrial protein responsible for thermogenic respiration, a specialized capacity of brown adipose tissue and beige fat that participates in non-shivering adaptive thermogenesis to temperature and diet variations and more generally to the regulation of energy balance (By similarity). Functions as a long-chain fatty acid/LCFA and proton symporter, simultaneously transporting one LCFA and one proton through the inner mitochondrial membrane. However, LCFAs remaining associated with the transporter via their hydrophobic tails, it results in an apparent transport of protons activated by LCFAs. Thereby, dissipates the mitochondrial proton gradient and converts the energy of substrate oxydation into heat instead of ATP. Regulates the production of reactive oxygen species/ROS by mitochondria (By similarity).
Synonyms: SLC25A7; UCP
Tractability: Small molecule: a structure with a bound ligand is known. Antibody: UniProt predicts a signal peptide or a membrane-spanning region.
Gene: Protein-coding gene on chromosome 4 (140,559,431 to 140,569,001, reverse strand). Ensembl gene ENSG00000109424.
Subcellular location: Mitochondrion inner membrane
Pathways (Reactome):
Metabolism: Mitochondrial Uncoupling; The fatty acid cycling model
Developmental Biology: Transcriptional regulation of brown and beige adipocyte differentiation by EBF2
Gene Ontology:
Molecular function: long-chain fatty acid binding; proton transmembrane transporter activity; transmembrane transporter activity; cardiolipin binding; oxidative phosphorylation uncoupler activity; purine ribonucleotide binding; anion binding; GDP binding; GTP binding
Biological process: proton transmembrane transport; adaptive thermogenesis; brown fat cell differentiation; cellular response to fatty acid; cellular response to hormone stimulus; cellular response to reactive oxygen species; mitochondrial transmembrane transport; positive regulation of cold-induced thermogenesis; regulation of reactive oxygen species biosynthetic process; response to cold; response to nutrient levels; response to temperature stimulus; cellular response to cold; cellular response to dehydroepiandrosterone; diet induced thermogenesis; mitochondrial transport; transmembrane transport
Cellular component: mitochondrial inner membrane; mitochondrion; mitochondrial envelope
Genetic constraint (gnomAD): Loss-of-function variants: 29 observed, 31.88 expected, observed/expected ratio (o/e) 0.91, 90% interval 0.68 to 1.24. The upper end of that interval is the gene's LOEUF score, 1.24, which puts it in group 5 of 6, group 1 being the genes least tolerant of losing a copy. Missense variants: 402 observed, 406.89 expected, observed/expected ratio (o/e) 0.99, 90% interval 0.91 to 1.07. Synonymous variants: 164 observed, 163.97 expected, observed/expected ratio (o/e) 1, 90% interval 0.88 to 1.14.
Homologues: Orthologues: chimpanzee UCP1 (99% identical), macaque UCP1 (95% identical), guinea pig UCP1 (82% identical), rabbit UCP1 (82% identical), mouse Ucp1 (79% identical), rat Ucp1 (79% identical), tropical clawed frog ucp1 (62% identical), dog UCP1 (61% identical), zebrafish ucp1 (61% identical). Paralogues in human: UCP3 (58% identical), UCP2 (57% identical), SLC25A14 (33% identical), SLC25A30 (33% identical), SLC25A27 (30% identical), SLC25A34 (27% identical), SLC25A12 (27% identical), SLC25A10 (26% identical), SLC25A11 (26% identical), SLC25A13 (26% identical), SLC25A21 (26% identical), SLC25A20 (25% identical), and 37 more.
Diseases named in the same sentence as UCP1 in open-access papers:
UCP1 is named in the same sentence as 194 diseases in open-access papers, as found by Europe PMC text mining. Sharing a sentence is not in itself a finding about the gene and the disease. The quoted sentences say what the papers report.
Obesity (833 papers, 2007 to 2026). Accumulation of substantial excess body fat. "Conversely, the ablation of UCP-1 results in reduced thermogenic capacity and increased susceptibility to diet-induced obesity." (PMID 40362353, 2025). "Surprisingly, Ucp1-deficient mice had a normal body weight and were resistant to diet-induced obesity, when housed at room temperature." (PMID 40702736, 2025). "At thermoneutrality, this Ucp1-independent mechanism is not activated explaining, at least in part, the susceptibility to obesity in Ucp1-deficient mice." (PMID 40702736, 2025). "Mice deficient in AhR expression were resistant to high fat diet (HFD)-induced obesity and had increased gene expression for energy expenditure through increased brown fat UCP1-linked thermogenesis and muscle fatty acid β-oxidation." (PMID 40867852, 2025). "Among the most commonly reported variants associated with obesity and diabetes is the ucp1 rs45539933 variant in the codon region." (PMID 40149950, 2025). "Risk alleles for obesity include the R variant of the β3-adrenergic receptor (β3AR) and the G variant of uncoupling protein 1 (UCP1)." (PMID 40292541, 2025). "Since RXRγ functions as a heterodimeric partner of PPARγ in adipose tissue, it is likely that these age/obesity-associated impairments in PPARγ would undermine RXRγ-PPARγ target gene activation, including UCP1." (PMID 40855678, 2025). "The identification of the ucp1 rs45539933 variant suggests that a polygenic background can influence the penetrance of pathogenic mutation related to obesity and lipid disorders." (PMID 40149950, 2025). "Since obesity is influenced by both risk genes (β3AR and UCP1) and eating behaviors, the impact of these risk genes was also examined." (PMID 40292541, 2025). "Conversely, ablation of UCP1 results in reduced thermogenic capacity and increased susceptibility to diet-induced obesity, indicating an intricate interaction between mechanisms regulating energy balance and those controlling BAT." (PMID 39119146, 2024). "It has been shown that the thermogenic protein UCP1 is associated with obesity-related metabolic diseases." (PMID 38702594, 2024). "Specifically, brown adipose tissue (BAT) is positively associated with an increased resistance to obesity, due to its thermogenic function in the presence of uncoupled protein 1 (UCP1)." (PMID 39063092, 2024). "The −3826 A/G polymorphism in the promoter of UCP1 is associated with obesity, type 2 diabetes, and hypertension." (PMID 39033153, 2024). "Obesity is associated with a loss of UCP1 (brown-like phenotype marker) and/or elevation of FABP4 (white-like phenotype marker)." (PMID 38784129, 2024). "An obesity-associated increase in LXRα is inversely associated with decreased Ucp1 expression in BAT." (PMID 38928386, 2024). "This occurred despite the downregulation of UCP1 expression and resulted in decreased susceptibility to diet-induced obesity." (PMID 38212382, 2024). "First, the acetylation of peroxysome proliferator-activated receptor (PPAR)γ (Lys 293) present in obesity and associated with aging, decreases UCP-1 mediated by the increase in adipisin and favors the whitening of BAT." (PMID 38731880, 2024). "The UCP1-deficient mouse model is commonly used to investigate the role of BAT in anti-obesity strategies." (PMID 37355753, 2023). "From a biological viewpoint, the anti-obesity effect of fucoxanthin is intricately linked to its influence on the protein and gene expressions of uncoupling protein 1 (UCP1) in white adipose tissue (WAT)." (PMID 37685100, 2023). "Numerous studies concerned the association of UCP1 polymorphisms with susceptibility to MetS, obesity, and T2DM." (PMID 37107547, 2023). "The genetic ablation of mitophagy in UCP1-expressing cells resulted in higher thermogenic capacity and protection against diet-induced obesity owing to the prevention of beige adipocyte loss." (PMID 36674862, 2023).
Obesity (continued). "Animal studies have shown that loss of UCP1-expressing subcutaneous adipocytes in early postnatal life predisposes to adult obesity." (PMID 38069028, 2023). "The deficiency of BMAL1 in adipocyte was shown to contribute to obesity, although increased Ucp1 expression levels were observed." (PMID 37293491, 2023). "Even though many aspects underlying the sex differences remain elusive, data suggest that hyperphagia of female UCP1-deficient mice blunts anti-obesity effects of FGF21 induced WAT browning." (PMID 37355753, 2023). "Decreased UCP1 expression and thermogenesis are associated with obesity, thus, the search for compounds, including C. intermedia polyphenols, that are able to upregulate UCP1 expression and potentially induce thermogenesis is escalating." (PMID 36835279, 2023). "Several studies suggest that carriers of the UCP1 gene polymorphism rs1800592 genotype GG or GA are at high risk of multifactorial diseases, including obesity, characterized by higher body weight and BMI, and type 2 diabetes." (PMID 38026570, 2023). "Deficiency of Ucp1 exacerbates dietary obesity-induced endothelial dysfunction, vascular inflammation and AS in mice." (PMID 37679676, 2023). "Previously, HRW was linked to an increase in UCP1 expression in the BAT of high-fat diet-induced obesity mice." (PMID 37259294, 2023). "In this study, we show that the promotional effect of TRPV1 deficiency on BAT whitening and obesity induced by UCP1 knockout relies on aggravated mitochondrial Ca2+ disorder and ROS production." (PMID 35043013, 2022). "Ucp1 knockout (KO) mice are cold-sensitive and susceptible to obesity at thermoneutrality, and overexpression of Ucp1 in fat prevents genetic obesity." (PMID 36509749, 2022). "Accordingly, UCP1-deficient mice are prone to develop obesity and insulin resistance when mice are fed a high-fat diet (HFD) and maintained at a thermoneutral temperature (30 °C)." (PMID 36012714, 2022). "Conversely, Ucp1−/− mice exhibit greater susceptibility to obesity at advanced age when reared on a high-fat diet (HFD)." (PMID 35406743, 2022). "Some research shows that diabetes and obesity development involves specific polymorphisms of the Ucp1 gene." (PMID 35323702, 2022). "In the adipose tissue, the inflammatory process associated with obesity is able to mediate catecholamine resistance, impairing UCP1 upregulation and HSL phosphorylation." (PMID 35112705, 2022). "Related to its role to increase energy expenditure, BAT mass and activity are inversely correlated with obesity and body mass index and certain UCP-1 polymorphisms are associated with obesity and obesity-related conditions." (PMID 36194650, 2022). "Some studies have reported that polymorphisms in UCP1 and β3AR have an effect on obesity even in children." (PMID 36291357, 2022). "In summary, the knockout of TRPV1 and UCP1 in mice at the same time induced severe obesity and obesity-associated hypertension." (PMID 35043013, 2022). "In fact, mice deficient in Ucp1 are susceptible to weight gain, whereas an excess of Ucp1 protects against diet-induced obesity." (PMID 35625895, 2022). "The evidence suggests that CB2R activation is a therapeutic target for mitigating obesity-associated inflammation and excess lipid storage in white adipose tissue by modulating perilipin expression, upregulating IL-4, and stimulating UCP-1 signaling." (PMID 34393784, 2021). "The rs1800592 of the UCP1 gene is associated with obesity in general and in the moderate obese group in particular." (PMID 34055005, 2021). "Our study found that obese mice have a significantly reduced BAT percentage and UCP1 expression, and microarray analyses showed that obesity was associated with reduced glycolipid metabolism." (PMID 34082784, 2021). "High fat diet induced obesity is reduced by inhibiting Thp1 or in Thp1 deficient mice and this correlates with activation of uncoupling protein 1 (UCP1) mediated thermogenesis." (PMID 34769340, 2021).
Obesity (continued). "Reporter assay revealed that insulin-like growth factor 2 mRNA-binding protein 2 (IGF2BP2/IMP2) is a type 2 diabetes- and obesity-associated gene that suppresses Ucp1 mRNA translation likely via both 5′- and 3′-UTRs." (PMID 33634052, 2020). "UCP1 is linked to the protection against diet-induced obesity (DIO) as an integral membrane protein unique to BAT mitochondria." (PMID 32614631, 2020). "To identify the controlling factors and molecular networks of paradoxical obesity resistance in UCP1-deficient mice, we apply an array of technologies, ranging from mouse metabolic phenotyping to global omics analyses." (PMID 32005798, 2020). "Several polymorphisms in the promoter, non-coding, and coding regions of UCP1 gene were found associated with obesity and type 2 diabetes." (PMID 33634052, 2020). "UCP-1 is a thermogenic protein located in mitochondria of brown adipose tissue and there is accumulating evidence that decreased expression of UCP-1 is linked to an increase in obesity and vice-versa." (PMID 33076522, 2020). "Initial studies using UCP1 knockout mice showed that the loss of UCP1 yielded a surprising protection from obesity." (PMID 32713230, 2020). "As adipose tissue plays an important role in thermogenesis, it is possible that the anti-obesity effect of EA is associated with UCP-1 signal-related mechanisms." (PMID 32180699, 2020). "Clearance of both lipids and glucose from the plasma by UCP1 stimulation has many implications for health, including reduction in the risk of type 2 diabetes, obesity, and cardiovascular disease." (PMID 31220223, 2020). "Several studies stated that there was a relation between reduced expression of UCP1 in adipose tissue of obese subjects and the polymorphism of the 3826G allele of UCP1 gene, which in turn associated with the obesity or other obesity disorders as DM2." (PMID 32197395, 2020). "Other specific UCP1 polymorphisms, such as rs1800592 and rs3811791, are associated with obesity and abnormal values of high-density lipoprotein (HDL), low-density lipoprotein (LDL) and triglycerides levels." (PMID 32069871, 2020). "In fact, obesity-resistant UCP1-deficient mice have increased resistance to obesity due to the inactivation of a major thermogenic mechanism that results in an increased expenditure of energy." (PMID 32290353, 2020). "Increased expression of the UCP-1 gene has also been associated with obesity control and insulin insensitivity in mice." (PMID 31827547, 2019). "BAT UCP1 protein amount correlates positively with fat mass and is associated with protection against further obesity." (PMID 30807213, 2019). "In mice, the loss of UCP1 leads to obesity, while BAT activation improves insulin sensitivity and serum lipid profiles, and is anti-obesogenic." (PMID 31370146, 2019). "Previous studies showed that UCP1-deficient mice are sensitive to cold, but paradoxically more resistant to diet-induced obesity." (PMID 31730675, 2019). "Alternative activated macrophages (AAMs) induced during H. polygyrus infection suppressed insulin resistance and inflammation associated with obesity and enhanced UCP1 expression in adipose tissues." (PMID 30962398, 2019). "The mutant allele G of SNP rs1800592 on UCP1 showed a significant association with obesity [OR, 1.52 (1.10–2.08); p = 0.009]." (PMID 30458724, 2018). "Many studies have reported that polymorphisms (rs1800592, rs10011540, rs3811791) of the UCP1 promoter region and rs45539933 and rs2270565 of the UCP1 coding region are associated with obesity and T2DM." (PMID 30458724, 2018). "This browning of WAT together with induction of UCP1 was associated with a reduced propensity to develop obesity accompanied with improved metabolic health." (PMID 30631281, 2018). "The presence of rs1800592 polymorphism in the UCP1 gene was first identified in 1994 in a pilot study conducted on 261 Canadian patients and was associated with obesity and weight gain." (PMID 30458724, 2018).
Obesity (continued). "Further, the casein-induced reduction in adiposity is associated with a reversal of the obesity-induced whitening of adipocytes in iBAT and induction of UCP1 expression." (PMID 30631281, 2018). "Brown adipose tissue (BAT) with its thermogenic function due to the presence of the mitochondrial uncoupling protein 1 (UCP1), has been positively associated with improved resistance to obesity and metabolic diseases." (PMID 30687113, 2018). "The rs1800592 and rs3811791 of UCP1 gene are associated with obesity in general and in the moderate-obese group in particular." (PMID 30458724, 2018). "The UCP1 gene is considered to be a candidate gene for obesity and T2DM as the polymorphism of this gene reduces the mitochondrial membrane potential and mediates proton leak." (PMID 30458724, 2018). "We therefore evaluated expression levels of fatty acid oxidation-associated enzymes and uncoupling protein 1 (Ucp1) in BAT by western blot using a diet-induced obesity C57BL/6J mouse model." (PMID 28955734, 2017). "The expression of UCP1 therefore regulates thermogenesis, energy expenditure, and oxidative stress, processes associated with the pathogenesis of obesity." (PMID 28360931, 2017). "The present study supports this scenario physiologically, and builds consistency into the relationships between cold adaptation and the risk of obesity, as it is related to UCP1." (PMID 28717127, 2017). "Induction of brown-like adipocytes (beige/brite cells) in white adipose tissue (WAT) suggests a new approach for preventing and treating obesity via induction of thermogenesis associated with uncoupling protein 1 (UCP1)." (PMID 27598888, 2016). "Several studies have shown that low expression of UCP1 can cause several metabolic diseases such as obesity, type II diabetes and diseases related to age." (PMID 28039439, 2016). "EHMT1 increases the production of UCP1, and the deletion of this gene causes insulin resistance and obesity in mice, while haploinsufficiency is related to obesity and insulin resistance in humans." (PMID 27528872, 2016). "Ucp1-/- mice with variable diet-induced obesity (DIO) and a deficiency in brown fat thermogenesis and B6." (PMID 26070086, 2015). "Among the UCP1 polymorphisms, the A3826G SNP in the promoter region has been associated with obesity, weight gain, and resistance to weight loss." (PMID 25713540, 2015). "The beta-3 adrenergic receptor (β3-AR) Trp64Arg and uncoupling protein 1 (UCP1) -3826 A > G polymorphisms have been reported to be associated with obesity and/or lipid metabolism in some populations." (PMID 25928572, 2015). "Multiple logistic regression analysis was used to assess the association of the β3-AR Trp64Arg and UCP1 -3826 A > G polymorphisms with overweight/obesity." (PMID 25928572, 2015). "UCP1 gene polymorphisms have been implicated in the pathogenesis of obesity and related metabolic disorders, including lipid disorders." (PMID 25928572, 2015). "The association between CIDEA and basal metabolic have also been elucidated in human obesity and it has been found that its expression is inversely associated with basal metabolic rate and uncoupling protein 1 (UCP1) expression." (PMID 26434764, 2015). "This study examined the possible association of the β3-AR and UCP1 polymorphisms with overweight/obesity or lipid variation in a Southwest Chinese population." (PMID 25928572, 2015). "There are several reports available concerning the effect of the UCP1 -3826A > G polymorphism on obesity or plasma metabolic parameters." (PMID 25928572, 2015). "ApoAI possesses an anti-obesity effect associated with an increase of energy expenditure and upregulation of UCP1 in brown fat." (PMID 24347528, 2014). "UCP-1 polymorphism is also associated with the development of obesity and diabetes in many human studies." (PMID 25144367, 2014).